YAP1 (Yes1 associated transcriptional regulator)
Description:
Transcriptional regulator with dual roles as a coactivator and corepressor. Critical downstream regulatory target in the Hippo signaling pathway, crucial for organ size control and tumor suppression by restricting proliferation and promoting apoptosis. The Hippo signaling pathway core involves a kinase cascade featuring STK3/MST2 and STK4/MST1, along with its regulatory partner SAV1, which phosphorylates and activates LATS1/2 in complex with their regulatory protein, MOB1. This activation leads to the phosphorylation and inactivation of the YAP1 oncoprotein and WWTR1/TAZ. Phosphorylation of YAP1 by LATS1/2 prevents its nuclear translocation, thereby regulating the expression of its target genes. The transcriptional regulation of gene expression requires TEAD transcription factors and modulates cell growth, anchorage-independent growth, and induction of epithelial-mesenchymal transition (EMT). Plays a key role in tissue tension and 3D tissue shape by regulating the cortical actomyosin network, acting via ARHGAP18, a Rho GTPase activating protein that suppresses F-actin polymerization. It also suppresses ciliogenesis by acting as a transcriptional corepressor of TEAD4 target genes AURKA and PLK1. In conjunction with WWTR1, regulates TGFB1-dependent SMAD2 and SMAD3 nuclear accumulation (By similarity). Synergizes with WBP2 to enhance PGR activity. [Isoform 2]: Activates the C-terminal fragment (CTF) of ERBB4 (isoform 3). [Isoform 3]: Activates the C-terminal fragment (CTF) of ERBB4 (isoform 3).
Synonyms: YAP65; YAP-1; COB1; YAP; YAP2; YKI
Tractability: Small molecule: a structure with a bound ligand is known; a high-quality ligand is known. Antibody: UniProt places it where antibodies can reach, with high confidence; its Gene Ontology location is reachable by antibodies, with high confidence. PROTAC: UniProt records ubiquitination sites on it; ubiquitination databases record sites on it; a small molecule that binds it is known.
Gene: Protein-coding gene on chromosome 11 (102,110,099 to 102,233,424, forward strand). Ensembl gene ENSG00000137693.
Subcellular location: Cytoplasm; Nucleus; Cell junction, tight junction; Cell membrane
Subcellular location (Human Protein Atlas): Nucleoplasm; Cytosol; Nucleoli
Pathways (Reactome):
Developmental Biology: Developmental Lineage of Pancreatic Ductal Cells; Differentiation of Keratinocytes in Interfollicular Epidermis in Mammalian Skin; EGR2 and SOX10-mediated initiation of Schwann cell myelination; Formation of axial mesoderm; Zygotic genome activation (ZGA)
Gene expression (Transcription): RUNX1 regulates transcription of genes involved in differentiation of HSCs; RUNX2 regulates osteoblast differentiation; RUNX3 regulates YAP1-mediated transcription; YAP1- and WWTR1 (TAZ)-stimulated gene expression
Signal Transduction: Nuclear signaling by ERBB4; Signaling by Hippo
Cellular responses to stimuli: Turbulent (oscillatory, disturbed) flow shear stress activates signaling by PIEZO1 and integrins in endothelial cells
Immune System: Regulation of PD-L1(CD274) transcription
Gene Ontology:
Molecular function: DNA-binding transcription factor binding; protein binding; transcription cis-regulatory region binding; transcription coactivator activity; transcription coregulator activity; transcription corepressor activity; chromatin binding; proline-rich region binding; RNA polymerase II cis-regulatory region sequence-specific DNA binding
Biological process: cellular response to gamma radiation; DNA damage response; hippo signaling; negative regulation of cilium assembly; negative regulation of epithelial cell apoptotic process; negative regulation of fat cell differentiation; negative regulation of gene expression; negative regulation of hippo signaling; negative regulation of transcription by RNA polymerase II; positive regulation of cell growth; positive regulation of DNA-templated transcription; positive regulation of epithelial cell proliferation; positive regulation of gene expression; positive regulation of osteoblast differentiation; positive regulation of transcription by RNA polymerase II; protein-containing complex assembly; regulation of neurogenesis; regulation of stem cell proliferation; response to progesterone; epithelial cell proliferation; organ growth; polarized epithelial cell differentiation; positive regulation of keratinocyte proliferation; positive regulation of protein localization to nucleus; cardiac muscle tissue regeneration; and 9 more
Cellular component: cytoplasm; cytosol; nucleolus; nucleoplasm; nucleus; plasma membrane; TEAD-YAP complex; cell-cell junction; bicellular tight junction; membrane; transcription regulator complex
Genetic constraint (gnomAD): Loss-of-function variants: 5 observed, 49.48 expected, observed/expected ratio (o/e) 0.1, 90% interval 0.052 to 0.21. The upper end of that interval is the gene's LOEUF score, 0.21, which puts it in group 1 of 6, group 1 being the genes least tolerant of losing a copy. Missense variants: 535 observed, 627.45 expected, observed/expected ratio (o/e) 0.85, 90% interval 0.79 to 0.92. Synonymous variants: 263 observed, 242.5 expected, observed/expected ratio (o/e) 1.08, 90% interval 0.98 to 1.2.
Cancer hallmarks: angiogenesis (promotes); escaping programmed cell death (suppresses); tumour promoting inflammation; invasion and metastasis (promotes); change of cellular energetics (promotes); invasion and metastasis (suppresses); escaping immune response to cancer (promotes); proliferative signalling (promotes); tumour promoting inflammation (suppresses); angiogenesis (suppresses)
Homologues: Orthologues: chimpanzee YAP1 (100% identical), macaque YAP1 (99% identical), pig YAP1 (98% identical), dog YAP1 (93% identical), mouse Yap1 (89% identical), rat Yap1 (88% identical), rabbit YAP1 (85% identical), guinea pig YAP1 (78% identical), tropical clawed frog yap1 (77% identical), Caenorhabditis elegans yap-1 (19% identical). Paralogues in human: WWTR1 (41% identical).
Diseases named in the same sentence as YAP1 in open-access papers:
YAP1 is named in the same sentence as 444 diseases in open-access papers, as found by Europe PMC text mining. Sharing a sentence is not in itself a finding about the gene and the disease. The quoted sentences say what the papers report.
breast cancer (200 papers, 2012 to 2025). A primary or metastatic malignant neoplasm involving the breast. "NSUN6 regulates the mammalian sterile 20-like kinase 1 (MST1) target gene of Yes-associated protein 1 (YAP1), leading to osteoclast differentiation and breast cancer bone metastasis." (PMID 40370440, 2025). "YAP1 expression has been associated with recurrent disease in prostate cancer and drug-resistant disease in hepatocellular, ovarian, pancreatic, and breast cancers." (PMID 36719743, 2023). "So far, there have been few studies reporting associations between YAP1 expression and favorable outcome in patients with luminal breast cancer." (PMID 37894401, 2023). "In HR+HER2− breast cancer, high YAP1 expression was associated with low HG, low Ki67 LI, and low ODX RS." (PMID 37894401, 2023). "It is a known transcriptional target of TGFβ signaling in sarcoma and has also been linked to YAP1 signaling and breast cancer cell motility." (PMID 37546702, 2023). "YAP1 expression was positively correlated with Notch1 in breast cancer, and CCL5/CCR5 activated YAP in tumor-associated macrophages." (PMID 37759462, 2023). "As tumor stiffness in breast cancer is associated with aggressive features affecting prognosis, we expected a correlation between high YAP1 expression and high ODX RS in this study." (PMID 37894401, 2023). "RUNX1 has also been shown to exert protection against epithelial-to-mesenchymal transition (EMT) by antagonizing the oncogenic effects of YAP1—a transcription co-factor implicated in breast cancer metastasis." (PMID 36831308, 2023). "We aimed to investigate the association between YAP1 activation and tumor stiffness in human breast cancer samples, using immunohistochemistry and shear-wave elastography (SWE)." (PMID 36291755, 2022). "On the other hand, we detected 1.39% amplification and 2.31 deep deletions in YAP1 and 0% somatic mutation in Metastatic Breast Cancer cohort (INSERM, PLoS Med 2016)." (PMID 34196131, 2022). "The data indicate that YAP1 is positively associated with invadopodia formation in breast cancer cells." (PMID 35773411, 2022). "Studies have reported that YAP1 functions as a tumor suppressor in breast cancer and is associated with favorable outcomes, whereas others have suggested that YAP1 acts as an oncogene." (PMID 36291755, 2022). "Earlier, we analyzed the YAP1 target gene signature derived from YAP1-expressing stable mammary epithelial cell lines and showed an association with survival outcomes of breast cancer patients from publicly available datasets." (PMID 35407556, 2022). "One such marker is YAP1, a transcription co-activator protein that shows association with poor prognosis of breast cancer." (PMID 35407556, 2022). "Detailed association studies of YAP1 target genes with breast cancer outcomes can further improve our understanding of the contribution of YAP1 to breast cancer progression and identify novel prognostic factors." (PMID 35407556, 2022). "In this study, YAP1 target gene signatures were further analyzed to shortlist genes dependent on YAP1 expression in tumor samples that are significantly associated with recurrent breast cancers." (PMID 35407556, 2022). "In this study, the nuclear expression of YAP1 was evaluated in a large number of breast cancer specimens, was found to be significantly associated with the occurrence of distant metastasis (HR 2.271, 95%CIs 1.109–4.650, P = 0.0249)." (PMID 33718163, 2021). "By antagonizing TP53INP1 and Yes1 associated transcriptional regulator (YAP1), upregulated miR-200a enhances drug resistance in breast cancer." (PMID 33117693, 2020). "In cancers, the abnormal expression of YAP1 causes uncontrolled cell growth and is connected with development of several cancer types including breast cancer." (PMID 31848326, 2019).
breast cancer (continued). "Using fibroblasts isolated from different stages of mouse mammary tumors it has been shown that activation of Yes-associated protein 1 (YAP1) in CAFs promotes matrix stiffening, cancer cell invasion, and angiogenesis." (PMID 30356678, 2018). "Yes-associated protein (YAP1) is frequently reported to function as an oncogene in many types of cancer, but in breast cancer results remain controversial." (PMID 24559095, 2014). "YAP1 was also proposed to be a tumor suppressor in breast cancer, as the target of loss of heterzygosity in 11q22 genomic region." (PMID 24810989, 2014). "For example, stable knockdown of YAP1 in the ER+ human breast cancer cell line MCF-7 resulted in complete loss of tumour formation in BALB/c nude mice." (PMID 24559095, 2014). "We show that in ER+ breast cancer, decreased YAP1 expression is associated with more aggressive features such as higher histological grade, increased proliferation and lymph node positivity." (PMID 24559095, 2014). "In a subset of breast cancers, the YAP1 protein expression was significantly decreased due to loss of heterozygosity, and shRNA knockdown of YAP1 increased migration, invasiveness, and enhanced tumor growth." (PMID 22396793, 2012). "Although previous studies have linked YAP1 to chemoresistance and poor outcomes, especially in triple-negative or basal-like breast cancer, our findings suggest that YAP1 may exert context-dependent effects." (PMID 40731926, 2025). "Du and colleagues showed that miR-223 may enhance the cell proliferation, migration, invasion, and EMT of breast cancer cells through the Hippo/Yes-associated protein 1 (Yap1) signaling pathway." (PMID 39125761, 2024). "YAP-1 protein is overexpressed in various cancers, including colorectal cancer, gastric cancer, hepatocellular carcinoma, breast cancer, hedgehog-associated medulloblastoma, esophageal and oral squamous cell carcinoma (SCC), leukemia and other solid tumors, and has been referred to as an oncogene." (PMID 37476371, 2023). "Overexpression of YAP1 was also proved to be associated with poorer prognosis in breast cancer." (PMID 37744228, 2023). "Similarly, YAP1 has previously been linked to oncogenic phenotypes in breast cancer cells by acting at the upstream level of the Notch pathway and upregulating JAG1 expression." (PMID 36476410, 2022). "However, an increase in RAD51, a gene involved in homologous recombination that is regulated by YAP1, is the only reported underlying mechanism explaining how YAP1 regulates DNA damage repair induced through cisplatin in breast cancer." (PMID 34689211, 2022). "To understand the association of YAP1 and its target expression in breast cancer, specifically in a subtype-specific manner, we attempted to analyze a YAP1 target gene signature derived from a mammary epithelial cell line for association with survival outcomes in breast cancer datasets." (PMID 35407556, 2022). "Additionally, Kaplan–Meier meta-analyses showed that a high expression of NDRG1 mRNA level is specifically significantly associated with RFS in breast cancer patients with high YAP1 expression." (PMID 35459269, 2022). "However, the association between clinical data and YAP1 expression in patients with breast cancer has been poorly explored." (PMID 33718163, 2021). "YAP1 protein was shown to be associated with outcomes in patients with luminal A breast cancer." (PMID 34445421, 2021). "For instance, Lehn and colleagues reported that YAP1 expression is inversely correlated with HG and tumor cell proliferation, and that low YAP1 mRNA levels are associated with decreased recurrence-free survival and tamoxifen-resistance in luminal A subtype breast cancer." (PMID 33718163, 2021). "Subsequently, YAP1 was reported to be associated with tumor progression and patients’ prognosis in various kinds of cancers including bladder cancer, breast cancer, gastric cancer, head and neck cancers, colorectal cancer, and pancreatic ductal adenocarcinoma (PAAD)." (PMID 34257617, 2021).
breast cancer (continued). "The sum of our results delineated that linc-OIP5 in breast cancer cells may act on the upstream of YAP1/Notch/NRP1 signaling circuit associated with tube formation abilities of HUVECs through an indirect cell–cell contact." (PMID 32046779, 2020). "Moreover, breast-cancer cases with upregulation of YAP1 expression after treatment were statistically associated with a shorter life expectancy (OS, p = 0.023)." (PMID 32365528, 2020). "However, the role of YAP1 remains debatable, because both gain and loss of YAP1 expression have both been reported in breast cancer (BC)." (PMID 30868052, 2019). "Furthermore, low YAP1 mRNA expression was significantly associated with a decreased recurrence-free survival in the luminal A breast cancer subgroup, independently of lymph node status or proximal, possibly co-deleted 11q22 genes." (PMID 24559095, 2014). "In the randomised breast cancer material studied here, decreased YAP1 expression was associated with increased proliferation in ER+ breast cancers, indicating a discrepancy between the ER+ cell line model and primary breast cancer data." (PMID 24559095, 2014). "This indicates 11q22 deletions as part of the explanation to the recurrent decreased YAP1 protein levels in breast cancer, but also supports the possibility of additional unknown mechanisms contributing to YAP1 protein loss in breast cancer." (PMID 24559095, 2014). "Furthermore, low YAP1 mRNA expression is independently associated with a worse outcome in the luminal A molecular breast cancer subgroup." (PMID 24559095, 2014). "As YAP1 loss is proposed to be an early event in breast cancer, YAP1 downregulation in cell lines such as MCF-7 might have to be assessed at much later time points in order to better correlate findings between primary tumour data and cell lines." (PMID 24559095, 2014). "To test this hypothesis, we firstly performed Kaplan–Meier analyses using the online Kaplan–Meier–Plotter breast cancer database and the results showed that high expression of YAP1 mRNA level is associated with poor recurrence-free survival (RFS) in breast cancer patients with high HJURP expression." (PMID 35459269, 2022). "Furthermore, we observed the pharmacological inhibition of YAP1 phenocopies RASSF1A-mediated suppression of ERα and FOXM1 expression, suggesting that drugs that target YAP1 might compensate for the loss of RASSF1A function in ER+ breast cancer cells." (PMID 34831091, 2021). "Hence, our results suggest that loss of YAP1 may confer aggressiveness in ER+ breast cancers independently of the established oncogenic CCND1 amplification." (PMID 24559095, 2014). "For instance, E2F1-mediated ectopic expression of PP1A promotes breast cancer progression via activation of YAP1." (PMID 41050059, 2025). "Among the screened 374 small molecule compounds, Abemaciclib, a highly selective CDK4/6 inhibitor approved by FDA for breast cancer treatment, exhibited the strongest inhibitory effect, reducing YAP1 activity by more than 70%." (PMID 40307228, 2025). "In breast cancer, YAP1 expression is particularly enriched in high-grade, hormone receptor-negative tumors, including triple-negative breast cancer (TNBC)." (PMID 40731926, 2025). "ERK1 activation has previously been shown to beassociated with a better prognosis for breast cancer patients, because it leadsto the blockage of the Hippo signaling pathway and one of its downstreamtargets, the YAP1 protein." (PMID 40264578, 2025). "Through the analysis of public gene expression databases, high levels of DUB3 and YAP1 were found to correlate with poor relapse-free survival in ovarian, pancreatic, and breast cancer." (PMID 39827153, 2025).